PDPN (podoplanin)
Diseases named in the same sentence as PDPN in open-access papers (continued):
Sharing a sentence is not in itself a finding about the gene and the disease.
osteosarcoma (20 papers, 2007 to 2025). A usually aggressive malignant bone-forming mesenchymal neoplasm, predominantly affecting adolescents and young adults. "In Osteosarcoma models expressing PDPN, anti-CLEC-2 monoclonal antibody (2A2B10) treatment reduced plasma concentrations of key pro-inflammatory cytokines and suppressed lung metastasis relative to control mice." (PMID 41573582, 2025). "A novel anti-PDPN monoclonal antibody, LpMab-7, had high sensitivity to detect metastatic lesions of osteosarcomas." (PMID 38504248, 2024). "High PDPN protein expression is significantly correlated with lung metastasis in patients with osteosarcoma." (PMID 34503278, 2021). "For example, PDPN was expressed in human fibrosarcoma cell lines and human osteosarcoma tissues, which are rare tumors in humans but are frequently observed tumors in dogs." (PMID 32380790, 2020). "For osteosarcoma cells, a podoplanin-mediated platelet activation led to a PDGF receptor (PDGFR) signaling ensued by Akt phosphorylation which fostered osteosarcoma cell proliferation." (PMID 30305116, 2018). "We previously compared the migration activities of PDPN-transfected osteosarcoma cells and parental cells and found that PDPN-transfected osteosarcoma cells exhibited a higher migration activity." (PMID 26416352, 2015). "A similar decrease in migration is seen on antibody cross-linking of Podoplanin in osteosarcoma cells." (PMID 25368330, 2014). "Conclusively, we studied the cell-type specific regulation of podoplanin expression in human MG63 versus Saos-2 osteoblast-like osteosarcoma cells." (PMID 17343736, 2007). "These antibodies are a new therapeutic strategy for PDPN-positive osteosarcoma." (PMID 38504248, 2024). "Patients with osteosarcoma may have ectopic expression of podoplanin in macrophages, and the interaction of clec-2-podoplanin stimulates the formation of cancer-related thrombosis, thus aggravating the patient's condition." (PMID 33415105, 2020). "The expression of human PDPN (hPDPN; 162 amino acids) has been reported in many cancers, including oral cancers, malignant brain tumors, esophageal cancers, lung cancers, malignant mesotheliomas, bladder cancers, testicular tumors, and osteosarcomas." (PMID 26416352, 2015). "The epigenetic event observed in our study may have provided a selection advantage to MG63 osteosarcoma cells and further clonal selection, considering that podoplanin recently has been assessed to contribute to tumour progression by circumventing epithelial-mesenchymal transition." (PMID 17343736, 2007). "Activated platelets secrete LPA and CLEC, which enhance the invasive ability of osteosarcoma through the LPA-LPAR1 axis and the interaction between platelet CLEC-2 and osteosarcoma podoplanin." (PMID 36212395, 2022). "2CP also inhibited TCIPA induced by the human osteosarcoma cell lines HOS and MG63, which express high levels of PDPN." (PMID 26528756, 2015). "Further analysis on the differences between metastatic and non-metastatic samples revealed six intersection genes—AIM2, RPL22L1, PDPN, PKIB, GZMA, and MDM2—that related to metastasis potential of osteosarcoma and the observed gene expression differences resulted from the changes in methylation." (PMID 36072791, 2022).
colorectal cancer (18 papers, 2010 to 2025). A primary or metastatic malignant neoplasm that affects the colon or rectum. "It has been reported that higher PDPN expression is associated with poorer outcomes in human colorectal carcinomas and is considered to be another promising method of targeting CAFs." (PMID 38275890, 2024). "PDPN-positive CAFs (podCAFs) are associated with poor prognosis in pancreatic and lung adenocarcinomas (AC) or with good prognosis in advanced colorectal carcinoma (CRC)." (PMID 39451200, 2024). "For colorectal cancer, it has been demonstrated that PDPN-positive CAF phenotype was associated with less aggressive tumors, whereas PDPN-low/α-SMAhigh or PDPN-low/S100A4high CAFs were associated with tumor progression." (PMID 33143259, 2020). "Conversely, PDPN-expressing fibroblasts indicate a favorable outcome in colorectal carcinoma and uterine cervical carcinoma." (PMID 24354864, 2013). "Similarly, in colorectal cancer, PDPN+ CAFs secrete CCL2 to establish a PDPN/CCL2/STAT3 autocrine feedback loop that maintains CAFs heterogeneity and, via paracrine signaling, activates STAT3 in ECs to drive angiogenesis." (PMID 41514658, 2025). "It has been recently described that positive podoplanin expression in stromal fibroblasts exerts a protective role against cell invasion and is a significant indicator of good prognosis in patients with advanced colorectal cancer." (PMID 20196862, 2010). "On daily diagnosis of early colorectal carcinoma (CRC), PDPN upregulation in the stroma is often encountered, suggesting PDPN-positive CAFs have emerged." (PMID 39451200, 2024). "This study identified Faecalibaculum rodentium as a novel probiotic that suppresses colorectal cancer (CRC) via acetate, which enhances CD8+ T-cell immunity by blocking PDPN-CLEC-2 and induces tumor cell apoptosis through PI3K/AKT/mTOR pathway." (PMID 40693815, 2025). "In this study, paraffin-embedded sections from 11 cases of human early-stage colorectal cancer (SM invasive carcinoma) were stained with CD34 antibody for vascular endothelium and podoplanin antibody for lymphatic endothelium at the deepest, central, and marginal sites of tumor invasion." (PMID 40243510, 2025).
malignant mesothelioma (17 papers, 2014 to 2025). A malignant neoplasm of the pleura or peritoneum, arising from mesothelial cells. "The positivity of mesothelial markers, such as WT1, calretinin, podoplanin and HBME1, along with clinical–radiological findings, helps to distinguish this peculiar variant of malignant mesothelioma from a metastatic adenocarcinoma from another site." (PMID 35204459, 2022). "All sarcomatoid-type malignant mesotheliomas were immunohistochemically positive for the markers vimentin and podoplanin." (PMID 25410479, 2014). "All biphasic-type malignant mesotheliomas were immunohistochemically positive for the markers vimentin, podoplanin, and pan-cytokeratin." (PMID 25410479, 2014). "All epithelioid-type malignant mesotheliomas were immunohistochemically positive for the markers pan-cytokeratin, podoplanin, and vimentin." (PMID 25410479, 2014). "Histopathological classification of tumors and, additionally, immunohistochemistry were conducted for podoplanin, pan-cytokeratin, and vimentin to compare induced tumors with malignant mesotheliomas occurring in humans." (PMID 25410479, 2014). "D2-40 (podoplanin) is commonly positive in malignant mesothelioma." (PMID 41235016, 2025). "Podoplanin (PDPN) is highly expressed in most malignant mesothelioma." (PMID 34685483, 2021). "In addition, increased expression of PDPN has been reported in numerous cases of solid tumors, including squamous cell carcinomas of the lungs, head and neck, malignant mesothelioma, and brain tumors." (PMID 32858947, 2020). "Therefore, PDPN is a promising therapeutic target for malignant mesothelioma." (PMID 34685483, 2021). "In humans, podoplanin staining in the absence of cytokeratin staining can be seen in several different sarcomas as well as in malignant mesothelioma." (PMID 24405760, 2014).
head and neck squamous cell carcinoma (16 papers, 2006 to 2024). A squamous cell carcinoma that arises from any of the following anatomic sites: lip and oral cavity, nasal cavity, paranasal sinuses, pharynx, larynx, and salivary glands. "Abnormal expression of PDPN was also involved in the invasion and metastasis of head and neck squamous cell carcinoma." (PMID 36156321, 2023). "This phenomenon has also been evident in head and neck squamous cell carcinomas, where miR-363-3p inhibits the expression of the transmembrane glycoprotein podoplanin." (PMID 33744854, 2021). "Podoplanin expression was frequently used for evaluating the lymphovascular density in head and neck squamous cell carcinoma." (PMID 29410757, 2017). "Podoplanin expression has been previously explored in other head and neck squamous cell carcinomas, such as oral and hypopharyngeal carcinomas, as well as in oral premalignancies." (PMID 20196862, 2010). "Our results are in agreement with a previous study that compared D2-40 and podoplanin on paraffin sections of a series of head and neck squamous cell carcinomas." (PMID 18307818, 2008). "Studies have shown that assessment of podoplanin expression in the epithelial cells can be used to predict the malignant transformation of potentially malignant disorders and the metastatic tendency of primary head and neck squamous cell carcinoma." (PMID 29410757, 2017). "In head and neck squamous cell carcinomas, ezrin was identified as a key molecule in tumor progression and metastatic behavior of neoplastic cells and it has been correlated with poor outcome, similarly to podoplanin." (PMID 25480364, 2014). "In terms of partial epithelial-mesenchymal transition (p-EMT), MYOSLID expression in head and neck squamous cell carcinoma (HNSCC) was closely correlated with Slug, PDPN, and LAMB3, and is a key regulator of tumor cell survival." (PMID 34257164, 2021).
lymphangioma (16 papers, 2007 to 2026). A benign lesion composed of dilated lymphatic channels. "Robust expression of intrinsic YFP was observed in LECs from IFA-induced lymphangioma in PDPN-Cre; LSL-YFP mice, showing the YFP-expressing LECs as the dominant cell population (80% of all nucleated cells) within the lymphangioma tissue." (PMID 30592710, 2018). "In purely lymphatic tumours (lymphangiomas and hygromas), high levels of podoplanin staining were found, whereas in purely vascular tumours, much lower levels of staining were found when compared to other known vascular endothelial markers." (PMID 18325094, 2008). "We have observed Tie2 expression in LECs sorted with anti-podoplanin antibodies from HDMECs, as well as Tie1 and Tie2 in LECs from lymphangioma patients." (PMID 17584927, 2007). "LECs from foreskin and lymphangioma had an almost identical pattern of lymphendothelial markers such as podoplanin, Prox1, reelin, cMaf and integrin-α1 and -α9." (PMID 17584927, 2007). "However, it is important to note that PDPN is also expressed in other vascular tumors, including benign lymphangiomas, atypical vascular lesions, and Kaposi sarcoma." (PMID 40666093, 2025). "In addition, in vivo administration of GCV to PDPN-tk mice (daily 50 mg/kg body weight) inhibited the formation of IFA-induced lymphangioma when compared to control (WT) mice." (PMID 30592710, 2018). "Notably, lymphangioma formation was not altered in control mice, including WT mice (with or without GCV treatment) and non-GCV-treated PDPN-tk mice." (PMID 30592710, 2018).
ovarian carcinoma (15 papers, 2006 to 2025). A malignant neoplasm originating from the surface ovarian epithelium. "Similar associations have been reported in other malignancies, most notably in lung, esophageal, and ovarian cancers, where podoplanin expression correlates with unfavorable clinical outcomes." (PMID 41228241, 2025). "Production of PDPN in the form of extracellular vesicles has been demonstrated in cases of ovarian cancer." (PMID 40741180, 2024). "The findings of this study suggest that PDPN in ovarian cancer cells stimulates tumor growth and leads to venous thrombosis in mice." (PMID 40741180, 2024). "Mouse models of ovarian cancer and venous thrombosis have been used to demonstrate that cancer cell production of podoplanin, a membrane glycoprotein on their surface and on released extracellular vesicles, mediates both tumor growth and thrombosis." (PMID 39518024, 2024). "PDPN expression in ovarian cancer cells promoted tumor formation, while suppression of PDPN expression resulted in smaller primary tumors in a mouse ovarian cancer model." (PMID 40741180, 2024). "The authors of the study reported that cisplatin and topotecan, two chemotherapy drugs frequently used to treat ovarian cancer, increase the expression of PDPN in cancer cells." (PMID 40741180, 2024). "Podoplanin overexpression in the malignant stroma of ovarian cancer patients predicts lymphatic spread and poor clinical outcomes." (PMID 36831623, 2023). "A diagnostic ROC (receiver operating characteristic) curve was used to determine the diagnostic significance of LRRC15, PDPN and CD8 as three independent indicators for primary platinum-resistant ovarian cancer." (PMID 36653841, 2023). "The binding of platelet-derived CLEC-2 to podoplanin on CAFs and cancer cells promote tumor growth and venous thrombosis in patients with ovarian cancer." (PMID 36831623, 2023). "Blocking podoplanin—CLEC-2 contact between ovarian cancer cells and platelets forestalls lymph vessel proliferation." (PMID 36831623, 2023). "In summary, the expression of LRRC15 contributes to the proliferation of PDPN + CAFs and promotes the formation of mesenchymal ovarian cancer." (PMID 36653841, 2023). "For example, leukocytosis in lung and colorectal cancer, neutrophilia and NETs in lung cancer, thrombocytosis in ovarian cancer, TF-positive microparticles in pancreatic cancer, and PDPN-positive microparticles in brain cancer are proposed primary pathways." (PMID 35565252, 2022). "Previous studies have shown that overexpression of PDPN in fibroblasts is significantly correlated with a poor prognosis in ovarian carcinoma." (PMID 25803614, 2015). "Ovarian cancer cells produce PDPN and release extracellular vesicles that are rich in PDPN." (PMID 40741180, 2024). "Additionally, podoplanin is upregulated in ovarian cancer cells, and extracellular vesicles released from these cells increase the likelihood of thrombosis." (PMID 36831623, 2023). "A t-SNE plot of the ovarian cancer single-cell RNA sequencing profile of the tumor microenvironment shows that COL11A1, ACTA2 (gene encoding for α-SMA), and PDPN are expressed in different, partially overlapping, ovarian CAF subsets, with COL11A1 exhibiting the most restricted expression." (PMID 36497028, 2022). "PDPN is more frequently expressed in OCCC than in other histologic types of ovarian cancer." (PMID 35565252, 2022). "Fibroblasts that differentiate into CAFs promote ovarian cancer invasion through the upregulation of several markers such as alpha-smooth muscle actin (α-MA), PDGFR, and podoplanin." (PMID 36831623, 2023). "LRRC15, PDPN, and CD8 have certain accuracy as single biomarkers in predicting the outcomes of platinum-based chemotherapy for ovarian cancer." (PMID 36653841, 2023). "PDPN promotes tumor growth, platelet aggregation, and VTE in murine models of ovarian cancer." (PMID 35565252, 2022).
ovarian carcinoma (continued). "Research in the ovarian cancer TME has identified at least four different CAF subpopulations that express distinct molecular signatures characterized by variable expression of CD29, CD10, FAP, α-SMA, FSP1, PDGFR-β, podoplanin, and caveolin-1." (PMID 34201616, 2021). "A previous study in epithelial ovarian cancer using a polyclonal antibody to podoplanin showed that intratumoural LVD was not a statistically significant variable in overall or progression-free survival." (PMID 16685274, 2006).
breast tumors (14 papers, 2006 to 2025). "In infiltrating immune cells of breast tumors, transmembrane glycoprotein Podoplanin (PDPN) expressed on some tumor-associated macrophages (TAMs) is another binding partner of Gal-8." (PMID 40134029, 2025). "In breast tumor-infiltrating immune cells, PDPN was found highly expressed in tumor-associated macrophages (TAMs), and the latter spurs local stromal remodeling and promotes vascular growth and lymphatic infiltration." (PMID 35140786, 2022). "The same study reported that human breast tumors have similar CAF compositions and that the ratio between PDPN+ and S100A4+ CAFs was in TNBC associated with BRCA mutations." (PMID 40940764, 2025). "A multi‐layer spatial analysis of 693 breast tumours revealed a significant enrichment of PDPN‐expressing myofibroblasts at the border." (PMID 39350478, 2024). "Moreover, PDPN+ CAFs were detected in breast tumors of patients unresponsive to the treatment with trastuzumab (anti-HER2 monoclonal antibody)." (PMID 40940764, 2025). "In the breast tumor microenvironment, the transmembrane glycoprotein PDPN can bind to LEC-derived Gal-8, promoting integrin β1 activation in a glycosylation-dependent manner, leading to local matrix remodeling and increased angiogenesis and lymphatic invasion in breast cancer." (PMID 40134029, 2025). "In a previous study, we have shown that although LYVE-1 expression on LVs located at the tumour periphery was strong, no or weak immunoreactivity was found in intratumoral LVs and that podoplanin is the best marker to visualise LVs in and around primary breast tumours." (PMID 17088912, 2006). "Our analyses revealed that PDPN-expressing cells did not coexpress the breast-tumor–associated fibroblast marker αSMA but predominantly coexpressed the LEC-associated marker VEGFR3 and weakly coexpressed or failed to coexpress the vascular marker CD31, consistent with previous observations." (PMID 30592710, 2018). "In contrast, staining with the lymphatic vessel marker Podoplanin showed an opposite pattern with an increased number of peritumoral lymphatic vessels in the ER−tumors, suggesting that NCoR might also inhibit lymphangiogenesis in human breast tumors." (PMID 27806339, 2016). "Recently, a population of CD90+ mesenchymal cells found in human and mouse breast tumours contained subsets of FAP+PDPN+ and FAP+PDPN- cells with tumor growth-promoting properties; however, only the CD90+FAP+PDPN+ subset was immune suppressive." (PMID 34740105, 2021). "In human and mouse breast tumors, this direct immunosuppressive capacity of CAFs was attributed to a distinct subpopulation of fibroblasts expressing FAP and Podoplanin (PDPN)." (PMID 31428105, 2019).
angiosarcoma (13 papers, 2007 to 2025). A malignant tumor arising from the endothelial cells of the blood vessels. "Immunohistochemically, angiosarcomas exhibit membranous positivity for CD31 and nuclear positivity for ERG and variable positivity for CD34 (~50%), factor VIII-related antigen, FLI1, and D2-40 (podoplanin)." (PMID 40002892, 2025). "The function of podoplanin in human sarcomas, including angiosarcomas and Kaposi sarcoma, where the expression of podoplanin is often more diffuse and not restriced to the tumour front, needs to be elucidated." (PMID 17179989, 2007). "However, angiosarcoma tumor cells invariably show immunoreactivity for one or more endothelial markers (factor VIII, CD31, CD34), as well as epithelial markers such as cytokeratins and concomitant negativity for thyroglobulin or podoplanin (D240)." (PMID 40214777, 2025).